SIRT5 (sirtuin 5)
Description:
NAD-dependent lysine demalonylase, desuccinylase and deglutarylase that specifically removes malonyl, succinyl and glutaryl groups on target proteins. Activates CPS1 and contributes to the regulation of blood ammonia levels during prolonged fasting: acts by mediating desuccinylation and deglutarylation of CPS1, thereby increasing CPS1 activity in response to elevated NAD levels during fasting. Activates SOD1 by mediating its desuccinylation, leading to reduced reactive oxygen species. Activates SHMT2 by mediating its desuccinylation. Modulates ketogenesis through the desuccinylation and activation of HMGCS2 (By similarity). Has weak NAD-dependent protein deacetylase activity; however this activity may not be physiologically relevant in vivo. Can deacetylate cytochrome c (CYCS) and a number of other proteins in vitro such as UOX.
Synonyms: SIR2L5
Tractability: Small molecule: a structure with a bound ligand is known; a high-quality ligand is known; it has a high-quality binding pocket. PROTAC: ubiquitination databases record sites on it; its protein half-life has been measured; a small molecule that binds it is known.
Target class: Histone deacetylase; HDAC class III; Epigenetic regulator; Eraser
Gene: Protein-coding gene on chromosome 6 (13,574,210 to 13,615,158, forward strand). Ensembl gene ENSG00000124523.
Subcellular location: Mitochondrion matrix; Mitochondrion intermembrane space; Cytoplasm, cytosol; Nucleus; Cytoplasm (Isoform 1); Mitochondrion; Mitochondrion (Isoform 2)
Subcellular location (Human Protein Atlas): Mitochondria
Pathways (Reactome):
Metabolism: Urea cycle
Organelle biogenesis and maintenance: Transcriptional activation of mitochondrial biogenesis
Gene Ontology:
Molecular function: NAD+ binding; protein-glutaryllysine deglutarylase activity; protein-malonyllysine demalonylase activity; protein-succinyllysine desuccinylase activity; zinc ion binding; histone deacetylase activity, NAD-dependent; NAD+ poly-ADP-ribosyltransferase activity; NAD+-protein mono-ADP-ribosyltransferase activity; NAD-dependent protein lysine deacetylase activity; acyltransferase activity, transferring groups other than amino-acyl groups
Biological process: negative regulation of reactive oxygen species metabolic process; peptidyl-lysine demalonylation; peptidyl-lysine desuccinylation; protein deacetylation; protein deglutarylation; protein demalonylation; protein desuccinylation; mitochondrion organization; regulation of ketone biosynthetic process; urea cycle; chromatin remodeling; negative regulation of cardiac muscle cell apoptotic process; response to nutrient levels
Cellular component: cytosol; mitochondrial intermembrane space; mitochondrial matrix; mitochondrion; nucleus; cytoplasm; mitochondrial inner membrane
Genetic constraint (gnomAD): Loss-of-function variants: 20 observed, 30.67 expected, observed/expected ratio (o/e) 0.65, 90% interval 0.46 to 0.95. The upper end of that interval is the gene's LOEUF score, 0.95, which puts it in group 4 of 6, group 1 being the genes least tolerant of losing a copy. Missense variants: 360 observed, 381.89 expected, observed/expected ratio (o/e) 0.94, 90% interval 0.86 to 1.03. Synonymous variants: 142 observed, 146.36 expected, observed/expected ratio (o/e) 0.97, 90% interval 0.85 to 1.12.
Homologues: Orthologues: chimpanzee SIRT5 (99% identical), macaque SIRT5 (98% identical), pig SIRT5 (86% identical), mouse Sirt5 (86% identical), rat Sirt5 (85% identical), rabbit SIRT5 (84% identical), dog SIRT5 (82% identical), guinea pig SIRT5 (82% identical), tropical clawed frog sirt5 (77% identical), zebrafish sirt5 (69% identical). Paralogues in human: SIRT4 (27% identical), SIRT1 (26% identical), SIRT3 (24% identical), SIRT2 (23% identical), SIRT7 (21% identical), SIRT6 (20% identical).
Diseases named in the same sentence as SIRT5 in open-access papers:
SIRT5 is named in the same sentence as 162 diseases in open-access papers, as found by Europe PMC text mining. Sharing a sentence is not in itself a finding about the gene and the disease. The quoted sentences say what the papers report.
breast cancer (33 papers, 2016 to 2025). A primary or metastatic malignant neoplasm involving the breast. "The TCGA analysis of the breast cancer data base showed a very high correlation between Sirt5 expression and the expression of genes encoding proteins involved in the mTORC2-PKC-Nrf2-ATF4 signaling pathway described herein." (PMID 35963851, 2022). "Higher SIRT5 levels in breast cancer patients were associated with a poor prognosis." (PMID 36980194, 2023). "Although SIRT5 expression was found to be upregulated in breast cancer, which may be indicative of its role in breast cancer progression, only a few studies have revealed the mechanisms underlying the role of SIRT5 in breast cancer." (PMID 36291902, 2022). "In breast cancer, SIRT5 promotes tumor growth by desuccinylating and stabilizing glutaminase 1, thereby enhancing its enzymatic activity." (PMID 41304967, 2025). "Recently, SIRT5 has been reported to act as a tumor promoter in several cancer types, including ovarian and breast cancer, CRC,164, 165 AML,166 and melanoma." (PMID 39215785, 2025). "SIRT5 is another SIRT that plays an important role in cancer metabolism to promote breast cancer progression." (PMID 40165290, 2025). "In breast cancer, SIRT5 expression is significantly elevated, and knockout of SIRT5 can induce oxidative stress by increasing the succinylation of IDH2, leading to apoptosis in tumor tissues and inhibiting tumor growth." (PMID 39944690, 2025). "DK1-–04e is a selective, cell-permeable, and potent small-molecule SIRT5 inhibitor that effectively inhibits the growth of breast cancer cells in vitro and significantly suppresses mammary tumor development in vivo." (PMID 41304967, 2025). "SIRT5, a mitochondrial lysine deacylase, influences breast cancer metabolism by modulating glutamine metabolism, ROS accumulation, and autophagy/mitophagy." (PMID 41471349, 2025). "Genetic or pharmacological disruption of SIRT5 impedes breast cancer cell growth both in vitro and in vivo, suggesting its potential as a therapeutic target." (PMID 38773972, 2024). "SIRT5 inhibition significantly hampered breast cancer cell invasion and proliferation in high-glucose conditions, suppressed malignant transformation, and hindered lung metastasis in the MMTV-PyMT mouse model." (PMID 38315203, 2024). "For example, SIRT5-mediated GLS desuccinylation promoted the invasion of breast cancer cell by hampering the ubiquitination-dependent GLS degradation, while the deacetylation of GLS was also reported to contribute to the progression of various carcinomas." (PMID 38315203, 2024). "Heightened dependency on SIRT5 is exhibited by breast cancer cells, possibly due to increased oxidative stress." (PMID 38773972, 2024). "Given autophagy's dual role in tumor development, the impact of SIRT5 inhibition on breast cancer or other cancers requires further investigation." (PMID 38773972, 2024). "This was corroborated by the pharmacological inhibition of SIRT5, which significantly decreased tumour size in mouse xenograft models of breast cancer." (PMID 38213532, 2023). "It has been noted that SIRT5 promotes carcinogenesis and cell proliferation and is overexpressed in breast cancer." (PMID 36980194, 2023). "In breast cancer, SIRT5 was shown to reduce ATP levels, thus rendering cancer cells more vulnerable to chemotherapeutic agents and environmental stress." (PMID 36980194, 2023). "Increased levels of SIRT5 expression were for example detected in human breast cancer samples, and the resulting IDH2 desuccinylation accelerated its enzymatic activity and produced increased amounts of NADPH, thus combating the oxidative stress." (PMID 38213532, 2023). "In line with this, low levels of ammonia were discovered in MDA-MB-231 and C2C12 breast cancer cells overexpressing SIRT5, which reduced ammonia-induced autophagy and mitophagy." (PMID 36980194, 2023).
breast cancer (continued). "This led us to Sirt5, as we found a positive correlation between ATF4 and Sirt5 expression when analyzing data from The Cancer Genome Atlas (TCGA) breast cancer data set (3380 samples)." (PMID 35963851, 2022). "Despite the negative regulation of glycolysis by SIRT6, SIRT3 and SIRT5 were found to contribute to cancer cell proliferation and survival in diffuse large B cell lymphoma and breast cancer by regulating the function of metabolic enzymes." (PMID 35897717, 2022). "We show that mTORC2 enhances ATF4 expression and identify Sirt5 as an ATF4 transcriptional target which is necessary to promote breast cancer survival in response to metabolic stress." (PMID 35963851, 2022). "We next set out to establish that Sirt5 is a transcriptional target of ATF4 by examining the effects of knocking down its expression in breast cancer cells undergoing metabolic stress." (PMID 35963851, 2022). "As in breast cancer, SIRT5 was found to be highly expressed in prostate tumor tissues compared to normal prostate tissues." (PMID 36291902, 2022). "In breast cancer cells, sirtuin-5 (SIRT5), a mitochondrial NAD+-dependent lysine deacylase, was shown to stabilize GLS by desuccinylating GLS and preventing it from ubiquitin-mediated degradation." (PMID 36139432, 2022). "IDH2, an NADPH-generating enzyme, was identified as an SIRT-5 substrate in mammary tumors: SIRT-5 was demonstrated to desuccinylate and activate IDH2." (PMID 36080416, 2022). "Consistent with this deduction, a recent study established SIRT5 inhibition as a crucial promising therapeutic approach against breast cancer in vivo and in vitro." (PMID 36291902, 2022). "In breast cancer cells, SIRT5 desuccinylates and stabilizes glutaminase, which regulates the overall glutaminolysis, a key metabolic hallmark of cancers." (PMID 34650436, 2021). "Overall, DK1-04e studies showed that SIRT5 inhibition can be an effective treatment in breast cancer cells." (PMID 34650436, 2021). "Meanwhile, elevated SIRT5 expression in breast cancer mediates glutaminase desuccinylation and protects glutaminase from ubiquitin-mediated degradation; this effect has been associated with a poor prognosis in breast cancers." (PMID 33117804, 2020). "In breast cancer and mouse myoblasts cells SIRT5 silencing increases ammonia-induced autophagy through control of glutamine metabolism and mitophagy." (PMID 31608237, 2019). "Consistent with our results, SIRT5 was shown to be overexpressed in human NSCLC, triple-negative breast cancer, breast cancer with BRCA1 mutation subtypes, CRC, and HCC." (PMID 31456942, 2019). "For example, in breast cancer, the expression of SIRT5 had significant relation with tumor location, grade, and expression of estrogen receptor or progesterone receptor." (PMID 27990096, 2016). "However, high SIRT2 and SIRT5 expression also correlated with drug resistance profiles across multiple breast cancer lines and chemotherapies, underscoring their roles in chemoresistance mechanisms." (PMID 41471349, 2025). "A more recent study showed that SIRT5 inhibitors have antitumor activity in breast cancer models." (PMID 40165290, 2025). "SIRT5 can induce the expression of glutaminase and promote aerobic glycolysis in breast cancer." (PMID 40165290, 2025). "Pharmacological inhibition of SIRT5 was evaluated in vivo using a murine breast cancer model." (PMID 41304967, 2025). "Abril and coworkers developed a small molecule inhibitor of SIRT5 called DK1-04e that inhibited the metastatic properties of breast cancer cells through desuccinylation of various metabolic enzymes, e.g., IDH, GLS, SHMT2, and PKM2, and significantly impaired tumor growth in experimental mice." (PMID 39781339, 2025). "SIRT5, overexpressed in breast cancer, correlates with poor patient outcomes." (PMID 38773972, 2024).
breast cancer (continued). "Furthermore, treatment with compound 6 (50 μM) led to a rise in succinylated proteins in both mouse myoblasts (C2C12) and human breast cancer cells (MDA-MB-231) due to the suppression of SIRT5 desuccinylase activity." (PMID 36980194, 2023). "In breast cancer, stabilization of mitochondrial glutaminase (GLS) by SIRT5-mediated desuccinylation leads to enhanced proliferation and survival, serving substrates for numerous metabolic pathways, correlating to poorer breast cancer prognosis when found overexpressed." (PMID 35328633, 2022). "As such, the authors concluded that SIRT5 may promote breast cancer by mitigating ROS via one or several of its targets." (PMID 36291902, 2022). "Importantly, an in vivo study of SIRT5 knockout MMTV-PyMT mice supported the tumor-promoting effect of SIRT5 in breast cancer." (PMID 36291902, 2022). "To date, most studies suggest that SIRT5 acts as a tumor promoter in breast cancer." (PMID 36291902, 2022). "Moreover, the SIRT5 gene frequently shows an increase in duplication in specific cancer types, including uterine cancer, breast cancer, cutaneous and uveal melanomas, lung cancer, and lymphoma." (PMID 31817470, 2019). "Polletta and colleagues found that another SIRT5 inhibitor, MC3482, through modifying ε-N-glutamyl lysine, inhibited succinylation of GLS, thereby promoting autophagy in breast cancer cells and inhibiting tumor initiation and progression." (PMID 39781339, 2025). "For example, SIRT5 regulates glutamine metabolism by desuccinylating glutaminase (GLS), which has been demonstrated to promote breast cancer development." (PMID 39781339, 2025). "Previous studies have demonstrated SIRT5’s tumor-suppressive roles in PDAC and renal cell carcinoma, while others have reported an oncogenic function in breast cancers." (PMID 39201811, 2024). "In line with this, SIRT5 suppression severely reduced cell proliferation in MCF7 and MDA-MB-231 breast cancer cells." (PMID 36980194, 2023). "Studies suggest that increased expression of SIRT5 can reduce the production of ammonia, leading to a decline in autophagy and mitophagy in MDA-MB-231 and C2C12 human breast cancer cells." (PMID 37175631, 2023). "In contrast, the expression of these genes was highly correlated with Sirt5 in brain cancer (Pearson values: sin1 0.96; PRCA 0.92; Nrf2 0.96; ATF4 0.97) and demonstrated the characteristic bimodal distribution observed in breast cancer." (PMID 35963851, 2022). "The most promising and selective SIRT-5 inhibitor is DK1-04e, which is able to suppress mammary tumor growth in vitro and in vivo." (PMID 36080416, 2022). "Taken together, the authors concluded that SIRT5 expression regulates ammonia-induced autophagy and mitophagy of MDA-MB-231 breast cancer cells by inhibiting GLS activity." (PMID 36291902, 2022). "To follow up on the similarity between pathway gene expression patterns in breast cancer and brain cancer, we examined how the expression of ATF4 and/or Sirt5 was affected in the glioblastoma cell line LN229 upon glutamine withdrawal." (PMID 35963851, 2022). "Increased expression of SIRT5 is probably related to aerobic glycolysis and the activity of HK2 and PKM2 enzymes in promoting liver and breast cancer." (PMID 36614171, 2022). "Although one study has shown that SIRT5 regulates ammonia‐induced autophagy in human breast cancer cell lines MDA‐MB‐231, the functions of SIRT5 in autophagy in CRC remain largely obscure." (PMID 30443978, 2019). "Nε-glutaryllysine-based compound MC3482 inhibits SIRT5 and suppresses the desuccinylation activity of SIRT5 in human breast cancer cells (MDA-MB-231) and mouse myoblasts (C2C12) without affecting its expression." (PMID 39479446, 2024). "Moreover, SIRT5 has a dichotomous function in lung cancer, hepatocellular carcinoma (HCC), and breast cancer, demonstrating that its activity ultimately depends on the particular environment and not only on the kind of tissue or cancer type." (PMID 36980194, 2023).
breast cancer (continued). "Moreover, SIRT5 inhibition arrested proliferation and the anchorage-independent growth of MCF7 and MDA-MB-231 breast cancer cells." (PMID 36980194, 2023). "On the contrary, a recent study demonstrated that SIRT5 desuccinylates GLS at residue K164, stabilizing and protecting it from ubiquitin-mediated degradation and that SIRT5 expression promotes the proliferation and tumorigenesis of MDA-MB-231 breast cancer cells." (PMID 36291902, 2022). "Several recent studies have shown that SIRT5 may play a tumor-promoting role in multiple types of cancer, such as HCC, colon cancer, human osteosarcoma and breast cancer." (PMID 31817470, 2019). "Currently, SIRT5 and 6 have not been investigated in gastric cancer, but have been shown to be involved in other cancers, such as breast cancer, lung cancer, hepatocellular carcinoma, head and neck squamous cell carcinoma, and ovarian cancer." (PMID 29088792, 2017). "In the case of SIRT5, the most potent and cellularly active molecules described to date are the peptide derivatives 39b‐d and 39g166, 392, 394 and 40b,c395 which, used as prodrugs, displayed favorable anticancer effects in AML and breast cancer cellular and mouse models." (PMID 39215785, 2025). "SIRT5 could promote autophagy in CRC, and suppress autophagy in human breast cancer cells." (PMID 33516270, 2021). "For example, either the mRNA or protein expression of SIRT5 was found to be increased in non-small cell lung cancer (NSCLC), hepatocellular carcinoma (HCC), colorectal cancer (CRC), Waldenstrom macroglobulinemia, and breast cancer, compared to the levels in matched normal tissues." (PMID 31456942, 2019). "However, SIRT5 has also been reported as a suppressor of autophagy in the human breast cancer cell line MDA‐MB‐231, indicating that SIRT5 might act as both autophagy promoter and suppressor in a context‐dependent manner." (PMID 30443978, 2019).